LINC01587 (long independently transcribed non-coding RNA 1587)
Synonyms: AC1; C4orf6
Gene: Long non-coding RNA gene on chromosome 4 (5,518,179 to 5,527,801, forward strand). Ensembl gene ENSG00000082929.
Diseases named in the same sentence as LINC01587 in open-access papers:
LINC01587 is named in the same sentence as 1 disease in open-access papers, as found by Europe PMC text mining. Sharing a sentence is not in itself a finding about the gene and the disease.
LINC01587 shares sentences with these, for which no sentence is quoted: neuroblastoma (1 paper).